HNF1B (HNF1 homeobox B)
Diseases named in the same sentence as HNF1B in open-access papers (continued):
Sharing a sentence is not in itself a finding about the gene and the disease.
Kidney Cyst (9 papers, 2015 to 2026). Abnormal fluid filled sac within the kidney, either acquired or congenital. "For instance, the combination of autism spectrum disorder and insulin-dependent diabetes may suggest a 17q12 deletion, which encompasses the gene HNF1B and is associated with kidney cysts and diabetes syndrome." (PMID 39945861, 2025). "Finally, Hnf1B is expressed in the ureteric bud as well as in comma- and S-shaped bodies, and mutations in this gene lead to kidney cyst formation in mice." (PMID 30967415, 2019). "The insights gained about the Hnf1b factors from this study may ultimately help direct research about kidney cysts and renal birth defects in patients with Hnf1b deficiencies." (PMID 26024215, 2015). "Bilateral hyperechogenic kidneys and cystic dysplasia are most commonly observed in prenatal HNF1B cases, followed by kidney cysts after birth." (PMID 35474932, 2021). "Most common causes of hereditary kidney cysts are ARPKD, ADPKD, nephronophthisis, HNF1B-associated disease, tuberous sclerosis." (PMID 35474932, 2021). "HNF1B in the mouse and BICC1 in mice and Xenopus regulate the Pkd2 transcript, and mutations in either gene can lead to kidney cysts in mouse models." (PMID 30967415, 2019). "A prenatal detection of kidney cysts should always induce the clinician to perform genetic tests on fetal DNA, including the CMA, and the study of a panel of genes, including HNF1B, involved in the polycystic kidney diseases." (PMID 41009948, 2025). "HNF1B haploinsufficiency typically leads to young-onset non-immune diabetes and highly variable renal involvement, whose more frequent features are bilateral kidney cysts and renal hypodysplasia." (PMID 41009948, 2025).
renal agenesis (9 papers, 2012 to 2025). Renal agenesis (RA) is a form of renal tract malformation characterized by the complete absence of development of one or both kidneys (unilateral RA or bilateral RA respectively), accompanied by absent ureter(s). "Deletions of HNF1β have recently drawn significant attention in pediatric nephrology as an important cause of prenatally hyperechogenic kidneys, renal aplasia and renal hypodysplasia." (PMID 22583611, 2012). "Microdeletions on chromosome 17q12 encompassing the hepatocyte nuclear factor 1β (HNF1β) have recently been characterized as an important cause of prenatally hyperechogenic kidneys, renal aplasia and renal hypodysplasia, which represent an important cause of chronic renal failure among children." (PMID 22583611, 2012). "HNF1B mutations can not only lead to cystic dysplastic kidneys but also elicit more severe manifestations of CAKUT, including renal agenesis." (PMID 36522156, 2023). "One fetus out of four with bilateral renal agenesis was diagnosed with HNF1B (25%)." (PMID 37535131, 2024).
renal carcinoma (9 papers, 2013 to 2024). A carcinoma arising from the epithelium of the renal parenchyma or the renal pelvis. "On the other hand, HNF1B is a transcription factor that acts as a tumor suppressor in renal carcinoma through control of PKHD1 expression." (PMID 30942869, 2019). "HNF1B has been shown to harbor biallelic inactivation from germline and somatic hits in renal carcinoma." (PMID 28569218, 2017). "HNF1B expression, evaluated by immunohistochemistry, was significantly associated with clear cell histology across diverse gynecologic and renal carcinomas (P<0.001), as was hypomethylation of the HNF1B promoter (P<0.001)." (PMID 24040285, 2013). "Finally, among gynecologic carcinomas with cytoplasmic clearing, HNF1B immunostaining was linked to a 3.0-fold increased risk of clinically-significant venous thrombosis (P = 0.043), and with a 2.3-fold increased risk (P = 0.011) in a combined gynecologic and renal carcinoma cohort." (PMID 24040285, 2013). "Among these genes, PAX8 and HNF1B play a key role in renal carcinoma." (PMID 30942869, 2019).
renal cell carcinoma (9 papers, 2006 to 2020). "For instance, SNPs of HNF1B are associated with risk of multiple cancers, including prostate, ovarian, endometrial, and renal cell carcinomas." (PMID 32010612, 2019). "A similar effect has also been observed in renal cell carcinoma, where HNF1B expression correlated with malignant transformation and progression, with elevated levels of HNF1B expression in primary tumor associated with better prognosis." (PMID 27732966, 2016). "Using an immunohistochemical approach, and methylation and mutation analysis, we have investigated the expression, epigenetic, and genetic changes of HNF1B in 130 cases of renal tumours (121 renal cell carcinomas, 9 oncocytomas)." (PMID 33051485, 2020). "HNF1β expression is reduced in renal cell carcinoma compared with normal kidney tissue." (PMID 26464794, 2015). "HNF1β may functions as a tumor suppressor gene in renal cell carcinoma." (PMID 26464794, 2015). "The expression of Pax8 was positive, but the expression CK7 and HNF1β was positive and that of CD10 and ER was negative, which indicate that the tumor has the feature of clear cell carcinoma of the ovary, not renal cell carcinoma nor cholangiocarcinoma." (PMID 30117003, 2018). "The expression of Pax8 was positive, but the expression CK7 and HNF1β was positive and that of CD10 and ER was negative, which indicate that the tumor has the feature of clear cell carcinoma of ovary, not renal cell carcinoma nor cholangiocarcinoma." (PMID 30117003, 2018).
renal failure (9 papers, 2013 to 2024). "Furthermore, in our case, since infant renal anomalies due to HNF1b mutations may progressively deteriorate and evolve into kidney failure, dialysis and, eventually, kidney transplantation cannot be ruled out." (PMID 33259036, 2021). "From the perspective of mechanism and relevant evidence, the HNF1β gene variation is highly likely to be associated with the occurrence and development of T2DM and promote renal failure." (PMID 35480487, 2022). "The HNF1β scramble and knockdown mice were treated with 30 mg/kg cisplatin for 3 days to induce acute kidney injury." (PMID 33512774, 2021). "HNF1β and NF‐κB signalling pathway can indirectly regulate each other and play important roles in cisplatin‐induced acute kidney injury." (PMID 33512774, 2021). "Antenatal kidney-specific conditional inactivation of Hnf1b in mice induces polycystic kidney disease with lethal renal failure around three weeks after birth." (PMID 23704921, 2013). "Another subject with MODY HNF-1B had to be initiated on insulin in a context of infection and acute renal failure, and could reverse back to oral medication afterwards." (PMID 38331895, 2024). "However, it is possible that in patients with a longer duration of the disease, particularly HNF1B-MODY, renal insufficiency might play a role in shaping the miRNA transcription profile." (PMID 27059371, 2016).
chromophobe renal cell carcinoma (8 papers, 2007 to 2025). Chromophobe renal cell carcinoma is a rare subtype of renal cell carcinoma, originating from the intercalating cells of the collecting ducts and macroscopically manifesting as a well-circumscribed, highly lobulated, solid tumor that is usually diagnosed at an early stage. "Somatic deletion of HNF1B (in combination with germline mutation) has been reported in some chromophobe renal cell carcinomas, suggesting a possible tumor suppressor function." (PMID 24040285, 2013). "However, HNF1B mutations/deletions have been shown to lead to a variety of renal malignancies such as polycystic kidney disease or even supporting chromophobe renal cell carcinoma development." (PMID 31431624, 2019). "Transcription factor HNF1B is a master regulator of gene expression, and loss of HNF1B may enhance cellular survival and exacerbate the development of chromophobe renal cell carcinomas." (PMID 29158988, 2017). "HNF1β and S100A1 are useful biomarker for distinguishing renal oncocytoma and chromophobe renal cell carcinoma." (PMID 30466390, 2018).
endometrioid carcinoma (8 papers, 2013 to 2023). "While two-thirds of our clear-cell cases stained with HNF1β, 31.6% of serous carcinomas and 13.7% of endometrioid carcinomas expressed HNF1β, making HNF1β staining an unreliable marker in the clear cell versus serous/endometrioid differential." (PMID 33986807, 2021). "Immunohistochemistry identified high expression of HNF1B and low expression of low estrogen receptor alpha (ERa) in ovarian CCC, whereas high expression of ERa and low expression of HNF1B were observed in endometrioid carcinoma." (PMID 34067626, 2021). "Also, the positivity of HNF-1β in a subset of endometrioid adenocarcinoma prevents the use of this marker in the differential diagnosis between endometrioid and endocervical type of adenocarcinoma." (PMID 25884453, 2015). "Also, the expression of HNF1β, Napsin A, and AMACR markers was reported in 101 cases of serous carcinoma 7%, 1%, and 1% and in endometrioid carcinoma 37%, 5.3%, and 0%." (PMID 37383161, 2023). "The only tumors without cytoplasmic clearing that were found to express HNF1B were renal papillary carcinomas, some endometrioid carcinomas, and uncommonly gastrointestinal carcinomas." (PMID 24040285, 2013).
hyperparathyroidism (8 papers, 2018 to 2025). Hyperfunction of the parathyroid glands resulting in the overproduction of parathyroid hormone. "As expected, well-known features of HNF1B-related disease, i.e., hypomagnesemia (65%) and hyperparathyroidism (38.5%) were more frequently found than in mut- subjects." (PMID 34362049, 2021). "In patients with 17q12 deletions involving HNF1B, hyperparathyroidism and hypomagnesemia may contribute to significant cardiovascular risk." (PMID 31500578, 2019).
type 1 diabetes (8 papers, 2020 to 2025). "Among 1021 Chinese individuals with non‐type 1 diabetes in the training dataset, 19 (1.9%) individuals carried pathogenic or likely pathogenic variants in GCK (n = 6), HNF1A (n = 9), HNF1B (n = 3), or HNF4A (n = 1) genes." (PMID 40966384, 2025).
autosomal dominant polycystic kidney disease (7 papers, 2017 to 2025). Autosomal dominant form of polycystic kidney disease. "A similar inheritance pattern explained some rare severe and early onset cases of autosomal dominant polycystic kidney disease when hypomorphic PKD1 mutations were co-inherited with variants in the PKHD1 or the HNF-1β gene." (PMID 28334007, 2017). "HNF1B is known to regulate transcription of polycystic kidney and hepatic disease (PKHD1), uromodulin (UMOD) and polycystic kidney disease 2 (PKD2)." (PMID 29576871, 2018).
cholestasis (7 papers, 2017 to 2026). Impairment of the bile flow caused by obstruction within the liver, or outside the liver in the bile duct system. "Based on the current evidence, HNF1B has been included among the genetic causes of high GGT cholestasis derived from a cholangiocyte dysfunction, in both children and adults." (PMID 36672242, 2023). "The role of HNF1B in ciliogenesis emerged with ultrastructural analysis of 3 adults with late-onset cholestasis, demonstrating a significant loss of primary cilia in cholangiocytes, but no structural intra- or extrahepatic bile duct defects." (PMID 36672242, 2023). "After the exclusion of pathogenic variants in main inherited cholestasis-related genes, a hemizygous de novo deletion of HNF1B on chromosome 17 between base pairs 34,817,422 and 36,242,969 was found." (PMID 35884482, 2022). "Moreover, HNF1B downregulation and mutations in HNF1B have been associated with neonatal or late-onset cholestasis and with common cancers, including endometrial, prostate, ovarian, hepatocellular, renal and colorectal tumours." (PMID 35884482, 2022). "Moreover, our group has recently described an additional case of a child with high GGT-cholestasis due to a de novo missense pathogenic variant of HNF1B, thus implicating rare mutations in HNF1B in the pathogenetic role in cholestatic liver diseases with increased GGT." (PMID 36672242, 2023). "HCC was firstly reported in HNF1B deficiency in a 16-month-old newborn with a germline pathogenic variant in HNF1B, presenting renal hyperechogenicity, transient renal neonatal failure, and progressive neonatal cholestasis, ultimately evolving to micronodular cirrhosis and HCC." (PMID 36672242, 2023). "The degree of cholestasis was probably the consequence of different etiologies (the pituitary insufficiency and deletion of HNF1β)." (PMID 40256398, 2025). "Future research directions will help understanding the pathogenesis of PFIC-8 and its relationship with HNF1β-related cholestasis, hopefully unveiling novel targets for therapeutic intervention." (PMID 36672242, 2023). "A paucity of interlobular bile ducts was reported in a few infants with cholestasis, high GGT values and HNF1B mutations similarly with Alagille syndrome." (PMID 35884482, 2022). "Only a single case of HCC and HNF1B was described: an infant having renal disease and progressive cholestasis from early months of life, developed a large liver cancer at 16 months, associated with an elevated AFP level." (PMID 35884482, 2022). "We describe the workup and follow-up of an infantile case of severe cholestasis in a patient with syndromic features (including hypopituitarism secondary to PSIS) and a final diagnosis of 17q12 deletion syndrome (including the HNF1β gene)." (PMID 40256398, 2025). "We suggest that HNF1β deficiency should also be ruled out, taking into consideration HNF1β mutations, together with Alagille syndrome, in next generation sequencing strategies in neonates with cholestasis, renal impairment and/or paucity of interlobular bile ducts at liver biopsy." (PMID 30791938, 2019).
Hypertension (7 papers, 2021 to 2025). The presence of chronic increased pressure in the systemic arterial system. "Patient 8 and 9 (HNF1B variant c.526C > T p.(Gln176*)) developed hypertension in childhood and adulthood, respectively." (PMID 36793123, 2023). "Dyslipidemia and hypertension were most common in HNF1B‐MODY (52.9% dyslipidemia, 58.3% hypertension) and KLF11‐MODY (75% dyslipidemia, 100% hypertension), while were less common in ABCC8‐MODY (18.2% dyslipidemia, 25.0% hypertension)." (PMID 39511990, 2024). "Among the children displaying hypertension within the first year of life (n = 12), the majority was diagnosed with ARPKD (n = 6), followed by biallelic ADPKD, TSC–PKD1 contiguous syndrome (n = 2, respectively), ADPKD (n = 1), and HNF1B-related disorder (n = 1)." (PMID 39384646, 2025).
renal dysplasia (7 papers, 2015 to 2025). Renal dysplasia is a form of renal malformation in which the kidney(s) are present but their development is abnormal and incomplete. "Recently, several genetic mutations, mainly associated with Six2, Wnt, Bmp7, and Hnf1β, and copy number variations have been identified in patients with renal dysplasia." (PMID 34395519, 2021).
renal malformation (7 papers, 2019 to 2024). "At the time of writing, the commonest mutated gene associated with cystic dysplastic kidneys is hepatocyte nuclear factor 1B (HNF1B); for example, pathogenic heterozygous variants of HNF1B were reported in 52 of 199 children with kidney malformations." (PMID 34838308, 2022). "We performed a retrospective analysis of clinical, biochemical, and genetic results of pediatric patients with renal malformations tested for HNF1B mutations, separated into 4 age groups." (PMID 31517149, 2019). "Many studies suggest that CNVs contribute to the etiology of RHD and implicate the genes within the CNV loci (e.g., PAX2, HNF1B, KIF26B, which are associated with kidney defects), that are detected in up to 10% of individuals with kidney malformations." (PMID 32211073, 2020). "We thus decided to assess this in our cohort of children with renal malformations with and without identified HNF1B mutations." (PMID 31517149, 2019). "On the other hand, this is not an unexpected finding, as the highest likelihood of HNF1B mutation identification in children with both MODY5 and kidney malformations is only 38%." (PMID 38196016, 2024).
serous carcinoma (7 papers, 2013 to 2023). "Recent studies have found HNF-1β expression to a lesser extent in other ovarian and endometrial tumors including endometrioid, mucinous and, rarely, serous carcinoma." (PMID 25884453, 2015). "However, recent studies have found HNF-1β expression to a lesser extent in other tumor types including endometrioid, mucinous and, rarely, serous carcinoma and even in some non-neoplastic tissues." (PMID 25884453, 2015). "Previously, HNF1B was found to be expressed specifically in ovarian CCC (as compared to other histotypes), and recently HNF1B immunostaining was reported to be a sensitive (82.5% sensitivity) and specific (95.2% specificity) marker for the diagnosis of ovarian CCC (vs. high-grade serous carcinoma)." (PMID 24040285, 2013).
serous ovarian cancer (7 papers, 2015 to 2023). "After identifying causal SNPs in the HNF1B region, the SNP‐HNF1B promoter DNA methylation was found to overlap with a polycomb repressive complex 2 mark in serous ovarian cancer." (PMID 33580750, 2021). "Alternatively, the negative correlation in methylation: expression patterns indicate a tumour suppressor role of HNF1B in high grade serous ovarian cancer." (PMID 33580750, 2021). "Knockdown of HNF1β in ovarian CCC cells resulted in a significant increase in proliferation, while overexpression of HNF1β in the serous ovarian cancer cell line caused cell growth to be significantly decreased." (PMID 26464794, 2015). "Ablation of HNF1B expression in ovarian CCC cells leads to a substantial proliferation, while increased expression of HNF1B in the serous Ovarian cancer (OC) cell line decreased cell growth." (PMID 33580750, 2021). "In addition, the same group recently investigated PCDH17 gene methylation (with other genes namely CDH13, HNF1B and GATA4) in high grade serous ovarian carcinoma." (PMID 36698136, 2023). "Furthermore, 60 % of the cells showed nuclear staining for the biomarker HNF1β, a protein considered to be pivotal in the pathogenesis of O-CCC as evolving from endometrioid lesions, and found to have high sensitivity and specificity to differentiate O-CCC from high-grade serous ovarian cancers." (PMID 26405433, 2015). "The effect on cell proliferation upon HNF1β knockdown was studied in five high‐ and low‐HNF1β‐expressing CCC cell lines and one high‐grade serous ovarian cancer (HGSOC) control cell line (PEO1), which does not express HNF1β." (PMID 27918136, 2017).